RASSF2 (Ras association domain family member 2)
Diseases named in the same sentence as RASSF2 in open-access papers (continued):
Sharing a sentence is not in itself a finding about the gene and the disease.
nasopharyngeal carcinoma (3 papers, 2009 to 2021). A carcinoma arising from the nasopharyngeal epithelium. "In addition, inactivation of the A isoform of RASSF2 by promoter methylation has been found to correlate with a higher frequency of lymph node metastases in patients with nasopharyngeal carcinoma." (PMID 19781100, 2009).
ovarian endometriosis (3 papers, 2019 to 2025). A non-neoplastic disorder characterized by the growth of endometrial tissue in the ovaries. "RASSF2 has been reported to be associated with ovarian endometriosis." (PMID 31552087, 2019).
prostate carcinoma (3 papers, 2009 to 2020). A carcinoma that arises from epithelial cells of the prostate gland. "RASSF2, which is a tumor-suppressor in the prostate cancer mouse model, might be coregulated by FXR1, FXR2, HNRNPA1, PTBP1, G3BP1, HNRNPF, and SRSF7." (PMID 32316190, 2020). "With regard to RASSF2 and SNRPB, Goodzari and co-workers found evidence for a prostate cancer metastasis suppressor gene on the short arm of human chromosome 20." (PMID 19781100, 2009).
breast neoplasm (2 papers, 2015 to 2017). A benign or malignant neoplasm of the breast parenchyma. "The hypermethylation of RASSF1 and RASSF2 genes was analyzed in 198 breast tumors of different subtypes." (PMID 26284587, 2015). "RT-PCR was performed to analyze RASSF2 expression in control and treated cell lines and in breast tumors." (PMID 26284587, 2015).
colon cancer (2 papers, 2005 to 2021). "Our results show that the hypermethylation of the RASSF2 gene promoter is frequent and associated with poorer survival in 229 patients with colon cancer." (PMID 34885067, 2021). "We found the RASSF/Hippo pathway to be highly silenced in colon cancer, and particularly RASSF2 (86%)." (PMID 34885067, 2021). "This first report of a whole systematic analysis of the Hippo pathway in colon cancer highlights RASSF2 gene promoter hypermethylation as a worst prognostic factor and a tool to be sought in clinical practice to improve therapeutic management." (PMID 34885067, 2021). "Analysis of the influence of the expression level of RASSF2 mRNA was performed in 438 patients with colon cancer." (PMID 34885067, 2021). "In conclusion, RASSF2 hypermethylation is a frequent event and an independent poor prognostic factor in colon cancer." (PMID 34885067, 2021). "Finally, we questioned the TCGA database to test if RASSF2 gene promoter hypermethylation predicts worse overall survival in the 229 patients with colon cancer from our collection is consistent in another cohort." (PMID 34885067, 2021). "The median OS was 53.5 months for patients with colon cancer with a hypermethylated RASSF2 promoter versus still not reached after 80 months follow-up for other patients, upon univariate analysis (HR = 1.86, [95% CI: 1.05–3.3], p < 0.03)." (PMID 34885067, 2021).
colorectal adenoma (2 papers, 2007 to 2021). An adenoma that arises from the colon or rectum. "In this study, therefore, we investigated K-ras and BRAF mutations and the methylation status of RASSF1 and RASSF2 in colorectal adenoma samples." (PMID 17923875, 2007). "We analysed K-ras/BRAF mutations and the methylation status of RASSF1 and RASSF2 promoter regions in 120 colorectal adenomas with respect to their clinicopathological features." (PMID 17923875, 2007). "In the current study, we examined K-ras/BRAF mutations and methylation status of RASSF1 and RASSF2 in colorectal adenomas in relation to clinicopathological features." (PMID 17923875, 2007).
Colorectal tumours (2 papers, 2005 to 2007). "In conclusion, we demonstrated that RASSF2 methylation is of importance as well as K-ras/BRAF mutations during the progression of colorectal tumours." (PMID 17923875, 2007). "Colorectal tumours with RASSF2 methyaltion showed K-ras/BRAF mutations significantly more frequently than those without RASSF2 methyaltion, although earlier studies have showed that K-ras mutation and RASSF2 methylation are mutually exclusive." (PMID 16265349, 2005).
Ewing sarcoma (2 papers, 2021 to 2024). A small round cell tumor that lacks morphologic, immunohistochemical, and electron microscopic evidence of neuroectodermal differentiation. "Similarly, in another type of gene, the gene RASSF2 was shown to be an oncogene for Ewing sarcoma, and high GIMAP4 expression could facilitate the TME of immune cells to detect tumor cells and inhibit the development of lung adenocarcinoma cells." (PMID 38688945, 2024).
lung adenocarcinoma (2 papers, 2024). A carcinoma that arises from the lung and is characterized by the presence of malignant glandular epithelial cells. "The results showed that IRF8, RASSF2, and EVI2B were significantly downregulated in lung adenocarcinoma tumors." (PMID 39049031, 2024). "We further investigated the expression of IRF8, CD4, RASSF2, and EVI2B in myeloid subtypes of lung adenocarcinoma." (PMID 39049031, 2024).
melanoma (2 papers, 2018 to 2024). A malignant, usually aggressive tumor composed of atypical, neoplastic melanocytes. "For example, in the field of cancer research, it has been used to model the RAB38 protein (Ras related protein 38), relevant in melanoma and RASSF2 (Ras Association Domain Family Member 2), studied in different tumor types." (PMID 30340325, 2018). "NF1-mutant melanomas preferentially harbored alterations in RASopathy genes, with SPRED1, RASA2, and RASSF2 being identified as significantly mutated genes within the subtype." (PMID 38758740, 2024).
Oral squamous cell carcinomas (2 papers, 2010 to 2012). "Methylation of RASSF1A and RASSF2 was associated with poor outcome after radiotherapy in oral squamous cell carcinoma." (PMID 20920251, 2010). "Oral squamous cell carcinomas in which RASSF2 is methylated showed higher levels of activated AKT." (PMID 22693671, 2012).
RASopathy (2 papers, 2017 to 2024). Developmental syndromes caused by germline mutations (or in rare cases by somatic mosaicism) in genes that alter the Ras subfamily and mitogen-activated protein kinases that control signal transduction. "Searching for co‐occurring mutated genes revealed the RASopathy genes PTPN11 and RASA2, as well as another RAS domain‐containing gene RASSF2 enriched in the NF1 subtype after adjustment for mutational burden." (PMID 28267273, 2017). "Herein, we confirmed that mutations in the RASopathy genes RASA2 and PTPN11 were enriched in the NF1 subtype and also identified RASSF2, a RAS domain‐containing gene, as enriched in the NF1 subtype." (PMID 28267273, 2017).
thyroid cancer (2 papers, 2010 to 2015). "Here we report that the degree of RASSF2 methylation was associated with the age of thyroid cancer patients." (PMID 20920251, 2010). "Here we report that RASSF2, a member of the Ras Association Domain family, is frequently silenced in primary thyroid tumor and thyroid cancer cell lines." (PMID 20920251, 2010). "This was also described in thyroid cancer cells, in which overexpression of RASSF2 reduced colony formation, because RASSF2 interacts with the proapoptotic kinases MST1 and MST2 and induces apoptosis in these cells." (PMID 26284587, 2015). "Here, we report that RASSF2 is frequently hypermethylated in thyroid tumors and suppresses growth of thyroid cancer." (PMID 20920251, 2010). "The thyroid cancer cell line 1736 was transfected with a construct expressing RASSF2 under control of the CMV promoter or an empty vector." (PMID 20920251, 2010). "RASSF2 methylation was significantly increased in primary thyroid carcinoma compared to normal thyroid, goiter and follicular adenoma (0%, 17% and 0%, respectively; p < 0.05)." (PMID 20920251, 2010). "We also show that RASSF2 suppressed growth of thyroid cancer cells." (PMID 20920251, 2010). "Expression of RASSF2 was reduced in several thyroid cancer cell lines (e.g. FTC 236 and 1736)." (PMID 20920251, 2010). "RASSF2 was methylated in 88% of thyroid cancer cell lines and in 63% of primary thyroid carcinomas." (PMID 20920251, 2010). "In summary, we report frequent tumor-specific hypermethylation of RASSF2 in thyroid cancer." (PMID 20920251, 2010). "Over-expression of RASSF2 reduced colony formation of thyroid cancer cells." (PMID 20920251, 2010). "Therefore, we analyzed RASSF2-induced growth suppression and apoptosis in thyroid cancer cell lines." (PMID 20920251, 2010). "Overexpression of RASSF2 induces apoptosis in thyroid cancer cell lines." (PMID 20920251, 2010). "Thus, it will be interesting to determine hypermethylation of RASSF2 in blood samples of thyroid cancer patients." (PMID 20920251, 2010). "In summary, we observed frequent epigenetic silencing of RASSF2 and RASSF5A in thyroid cancer cell lines." (PMID 20920251, 2010). "Next we analyzed the expression of RASSF2, RASSF5A and RASSF5C in all thyroid cancer cell lines and human fibroblasts (HF53)." (PMID 20920251, 2010). "Functionally our data show that RASSF2 interacts with the proapoptotic kinases MST1 and MST2 and induces apoptosis in thyroid cancer cell lines." (PMID 20920251, 2010). "Additionally, two thyroid cancer cell lines (FTC 236 and 1736) were treated with 5-Aza-2'-deoxycytidine (Aza) and RASSF2 and RASSF5A expression was analyzed by qRT-PCR." (PMID 20920251, 2010).
aneurysm (1 paper, 2025). Bulging or ballooning in an area of an artery secondary to arterial wall weakening. "While FOSB and RASSF2 have established roles in AAA literature 17, 18, our study represents the first report implicating FAP in aneurysm pathology." (PMID 40520892, 2025).
brain tumors (1 paper, 2015). "Our objectives were to analyze the presence of methylation in the EPB41L3, RASSF2 and TSP-1 genes in brain tumors and its prognostic role in patients." (PMID 25621889, 2015). "In our study, TSP-1 hypermethylation was more frequent than RASSF2 hypermethylation, and more frequent in less aggressive grade I-II tumors than in more advanced grades (III-IV), which is evidence of the early presence of this alteration in brain tumors." (PMID 25621889, 2015).
diabetes (1 paper, 2018). "The analysis showed that six gene sets and three member genes of ACADSB, RASSF2, and KLF12 had significant associations with diabetes traits." (PMID 29503662, 2018). "Both meta-analyses presented consistent tests of DGE and the results showed that genes of ACADSB, RASSF2, and KLF12 had significant gene expression associations with diabetes traits." (PMID 29503662, 2018).
endometrial carcinoma (1 paper, 2014). A malignant tumor arising from the epithelium that lines the cavity of the uterine body. "We also found that two genes, RASSF2 and RUNX3, were reported to be associated with endometrial carcinoma." (PMID 25298284, 2014).
glioma (1 paper, 2025). A benign or malignant brain and spinal cord tumor that arises from glial cells (astrocytes, oligodendrocytes, ependymal cells). "Among the most strongly decreased candidates, we observed proteins related to DNA repair (FANCA, USP38, NET1), autophagy (BCAS3), cancer cell migration and/or invasion (RASSF2, KMO, BCAS3), as well as proteins that can be generally considered as pro-tumorigenic, particularly in glioma (KMO, BCAS3)." (PMID 39833546, 2025).
gynecological cancer (1 paper, 2015). "RASSF2 hypermethylation was associated with a worse prognosis of gynecological cancer, as we had demonstrated before." (PMID 26284587, 2015).
leukemia (1 paper, 2020). A malignant (clonal) hematologic disorder, involving hematopoietic stem cells and characterized by the presence of primitive or atypical myeloid or lymphoid cells in the bone marrow and the blood. "Using proximity-based biotin labeling we define the RASSF2-proximal proteome in leukemia cells and reveal association with Rac GTPase-related proteins, including an interaction with the guanine nucleotide exchange factor, DOCK2." (PMID 32029705, 2020). "Instead, we here define the RASSF2-proximal proteome in leukemia cells and demonstrate the critical importance of its endogenous interaction with Hippo kinases, MST1 and MST2, through the C-terminal SARAH domain." (PMID 32029705, 2020). "Together, these data reveal a previously unappreciated mechanistic link between RASSF2, Hippo kinases, and Rac activity with potentially broad functional consequences in leukemia." (PMID 32029705, 2020). "Co-expression of Rassf2 significantly delayed RE9a leukemia onset (median survival 214 vs 150 days) compared to an empty-vector control." (PMID 32029705, 2020). "No additional canonical Hippo pathway components or SARAH domain-containing proteins were identified, demonstrating the discrete nature of a Hippo kinase-RASSF2 non-canonical signaling complex in leukemia cells." (PMID 32029705, 2020). "A proximity-based biotin labeling approach demonstrates that RASSF2 forms a discrete complex with MST1 and MST2 that is independent of the canonical Hippo pathway in leukemia cells." (PMID 32029705, 2020).
liver cancer (1 paper, 2012). An epithelial or non-epithelial malignant neoplasm that arises from the liver. "Altogether, the data indicate that inactivation of the RASSF1A tumor suppressor is ubiquitous in human liver cancer, while downregulation of RASSF2 and RASSF5 proteins is limited to specific HCC subsets." (PMID 22548173, 2012). "A downregulation of RASSF1A, RASSF2, NORE1A, and NORE1B proteins has been described in human liver cancer." (PMID 22548173, 2012). "Also, the present findings speak in favour of therapeutic strategies aimed at reexpressing RASSF1A, RASSF2, and RASSF5 genes and/or inactivating the RASSF cellular inhibitors for the treatment of human liver cancer." (PMID 22548173, 2012). "As concerns RASSF2, RASSF4, and RASSF5 isoforms (NORE1A and NORE1B), promoter hypermethylation seems to be the prominent mechanism responsible for their inactivation in liver cancer." (PMID 22548173, 2012).
malignant peripheral nerve sheath tumor (1 paper, 2015). Malignant peripheral nerve sheath tumor (MPNST) is a rare and often aggressive soft tissue sarcoma occurring in a wide range of anatomical sites. "RASSF2 is also downregulated in malignant peripheral nerve sheath tumors (MPNSTs) associated with neurofibromatosis type 1 relative to non-malignant plexiform neurofibromas, probably as a consequence of its hypermethylation." (PMID 25621889, 2015).
Merkel cell tumor (1 paper, 2013). "CpG island promoter methylation was analyzed for RASSF2, RASSF5A, RASSF5C and RASSF10 in Merkel cell tumor and skin control tissue." (PMID 24252868, 2013).
mismatch repair deficiency (1 paper, 2025). "Increased oxidative stress, inflammation-driven mismatch repair deficiency, and epigenetic alterations like RUNX3 and RASSF2 hypermethylation are implicated in carcinogenesis." (PMID 40364006, 2025).
myeloid leukemia (1 paper, 2020). A clonal proliferation of myeloid cells and their precursors in the bone marrow, peripheral blood, and spleen. "Our data suggest an important contribution by RASSF2 in cooperation with DOCK2 to this process in myeloid leukemia cells, which we reveal to have important consequences in AML." (PMID 32029705, 2020). "Strikingly, lentiviral shRNA-mediated knockdown of RASSF2 in myeloid leukemia cells with two independent shRNAs was sufficient to profoundly reduce endogenous Rac-GTP to ~ 30% of basal amounts." (PMID 32029705, 2020). "We therefore set out to study RASSF2 in the context of myeloid leukemia development." (PMID 32029705, 2020). "We could not, however, detect any evidence for nuclear localization of endogenous or exogenous RASSF2 in myeloid leukemia cell lines, while still replicating nucleo-cytoplasmic shuttling upon expression in HEK293T cells." (PMID 32029705, 2020). "This revealed that the ability of MST1 to interact with RASSF2 through the SARAH domain, rather than its kinase activity towards canonical effectors, contributes to its function in myeloid leukemia cells." (PMID 32029705, 2020).
oligodendroglial tumor (1 paper, 2015). Oligodendrogliomas are cerebral tumors that are differentiated from other gliomas on the basis of their unique genetic characteristics and better response to chemotherapy. "In conclusion, to the best of our knowledge, this is the first time that EPB41L3 and RASSF2 hypermethylation has been observed in astrocytic and oligodendroglial tumors." (PMID 25621889, 2015). "Our objectives were to analyze the presence of the hypermethylation of EPB41L3, RASSF2 and TSP-1 genes in 132 diffuse gliomas (astrocytic and oligodendroglial tumors) and in 10 cases of normal brain, and to establish their association with the patients’ clinicopathological characteristics." (PMID 25621889, 2015).
ovarian carcinoma (1 paper, 2014). A malignant neoplasm originating from the surface ovarian epithelium. "RASSF2 is widely expressed in humans and its down-regulation caused by aberrant promoter methylation had been found in a variety of primary malignant tumors and tumor cell lines, but it has not been reported to be related to ovarian cancer." (PMID 25298284, 2014).
prion disease (1 paper, 2012). A transmissible disease that is caused by a protein that is able to induce abnormal folding of normal cellular proteins, leading to characteristic spongiform brain changes, which are associated with neuronal loss without an inflammatory response. "Many studies that have examined the molecular mechanism of TSE have suggested the possibility that not only prnp, but also prnd, prnt, and the Ras association domain family 2 (RASSF2), are functionally associated with prion disease in humans." (PMID 22937002, 2012).
thyroid (1 paper, 2010). "Here we show that RASSF2 also acts as a novel tumor suppressor in thyroid carcinogenesis." (PMID 20920251, 2010). "The aim of our study was to reveal the epigenetic status and function of RASSF2, RASSF3, RASSF4, RASSF5 and RASSF6 in thyroid carcinogenesis." (PMID 20920251, 2010).
thyroid tumor (1 paper, 2010). A benign or malignant neoplasm affecting the thyroid gland. "Patients which were older than 60 years were significantly hypermethylated for RASSF2 in their primary thyroid tumors compared to those younger than 40 years (90% vs. 38%; p < 0.05)." (PMID 20920251, 2010). "Frequent methylation of the RASSF2 and RASSF5A CpG island promoters in thyroid tumors was observed." (PMID 20920251, 2010).